TCTN3 (tectonic family member 3)
Description:
Part of the tectonic-like complex which is required for tissue-specific ciliogenesis and may regulate ciliary membrane composition (By similarity). May be involved in apoptosis regulation. Necessary for signal transduction through the sonic hedgehog (Shh) signaling pathway.
Synonyms: C10orf61; TECT3; DKFZP564D116; JBTS18; OFD4
Tractability: Antibody: UniProt predicts a signal peptide or a membrane-spanning region. PROTAC: ubiquitination databases record sites on it.
Gene: Protein-coding gene on chromosome 10 (95,659,823 to 95,694,143, reverse strand). Ensembl gene ENSG00000119977.
Subcellular location: Membrane
Subcellular location (Human Protein Atlas): Microtubules
Pathways (Reactome):
Organelle biogenesis and maintenance: Anchoring of the basal body to the plasma membrane
Gene Ontology:
Molecular function: protein binding
Biological process: positive regulation of apoptotic process; smoothened signaling pathway; cilium assembly; protein localization to ciliary transition zone
Cellular component: nucleus; ciliary membrane; ciliary transition zone; MKS complex; membrane
Genetic constraint (gnomAD): Loss-of-function variants: 52 observed, 69.87 expected, observed/expected ratio (o/e) 0.74, 90% interval 0.6 to 0.94. The upper end of that interval is the gene's LOEUF score, 0.94, which puts it in group 3 of 6, group 1 being the genes least tolerant of losing a copy. Missense variants: 691 observed, 756.34 expected, observed/expected ratio (o/e) 0.91, 90% interval 0.86 to 0.97. Synonymous variants: 258 observed, 283.43 expected, observed/expected ratio (o/e) 0.91, 90% interval 0.82 to 1.01.
Gene-disease validity (ClinGen):
ClinGen rates the evidence that TCTN3 causes each of these diseases.
ciliopathy (autosomal recessive): Definitive. A genetic disorder of the cellular cilia or the cilia anchoring structures, the basal bodies, or of ciliary function.
Homologues: Orthologues: chimpanzee TCTN3 (99% identical), macaque TCTN3 (94% identical), pig TCTN3 (82% identical), rabbit TCTN3 (81% identical), dog TCTN3 (80% identical), guinea pig TCTN3 (76% identical), mouse Tctn3 (72% identical), rat Tctn3 (72% identical), tropical clawed frog tctn3 (33% identical), Caenorhabditis elegans tctn-1 (14% identical). Paralogues in human: TCTN1 (26% identical), TCTN2 (22% identical).
Diseases named in the same sentence as TCTN3 in open-access papers:
TCTN3 is named in the same sentence as 16 diseases in open-access papers, as found by Europe PMC text mining. Sharing a sentence is not in itself a finding about the gene and the disease. The quoted sentences say what the papers report.
Joubert syndrome (3 papers, 2020 to 2025). Joubert syndrome (JS) is characterized by congenital malformation of the brainstem and agenesis or hypoplasia of the cerebellar vermis leading to an abnormal respiratory pattern, nystagmus, hypotonia, ataxia, and delay in achieving motor milestones. "In summary, we report an additional patient with clinical signs of Joubert syndrome carrying two novel variants in the TCTN3 gene and exhibiting a thickened corpus callosum." (PMID 40565597, 2025). "Previous studies demonstrated that variants in TCTN3 lead to Joubert syndrome (JBTS18, OMIM #614815) that involves cardiac and skeletal defects." (PMID 33098376, 2020).
ciliopathies (2 papers, 2018 to 2021). "These ciliopathies are developmental diseases that follow a recessive pattern, with no symptoms found in carriers of the mutation, which is consistent our Tctn3 het KO mouse data." (PMID 29725084, 2018). "Tctn3 belongs to the Tectonic (Tctn) family and is a single-pass membrane protein localized at the transition zone of primary cilia as an important component of ciliopathy-related protein complexes." (PMID 29725084, 2018).
glioblastoma (2 papers, 2019 to 2024). The most malignant astrocytic tumor (WHO grade IV). "Dysfunction of the primary cilia, due to the loss of ciliary proteins like PCM1 (Pericentriolar Material 1) and TCTN3 (Tectonic Family Member 3), has been linked to increased apoptotic cell death in glioblastoma and neuronal cells in mice." (PMID 39201546, 2024). "In support of this notion, it has been recently reported that dysfunction of primary cilia by loss of ciliary proteins such as PCM1 and Tctn3 increases apoptotic cell death in glioblastoma or caused neuronal apoptosis in mice." (PMID 31844040, 2019).
orofaciodigital syndrome IV (2 papers, 2022 to 2025). Oral-facial-digital syndrome, type 4 is characterized by lingual hamartoma, postaxial polysyndactyly of hands and feet, and mesomelic shortening of the legs with supinate equinovarus feet. "Variants in the TCTN3 gene can lead to the development of several diseases, including JS type 18, Orofaciodigital syndrome IV, and Meckel–Gruber syndrome." (PMID 40565597, 2025). "Mutations in TCTN3 can cause several diseases, including JS type 18 (OMIM 614815), Orofaciodigital syndrome IV (OFD type IV, OMIM 258860), and Meckel–Gruber Syndrome (MKS, OMIM 249000)." (PMID 40565597, 2025). "Among the genetic causes associated with these phenotypes, pathogenic variants in DVL1/DVL3 and WNT5A (all (i.a.)for Robinow syndrome) and TCTN3 (orofaciodigital syndrome 4) have been identified." (PMID 34629465, 2022).
holoprosencephaly (1 paper, 2020). Holoprosencephaly (HPE) is a complex brain malformation resulting from incomplete cleavage of the prosencephalon, occurring between the 18th and 28th day of gestation, and affecting both the forebrain and face, which results in neurological manifestations and facial anomalies of variable severity. "TCTN3, the only gene detected in 3 species that encodes tectonic protein, functions in neural tube patterning, and causes holoprosencephaly and neural tube defects that are the most common risks of anomalies in the central nervous system." (PMID 32131728, 2020). "Tectonic protein gene TCTN3 functions in neural tube patterning and exhibits holoprosencephaly and neural tube defects in the mutant mice." (PMID 32131728, 2020).
Joubert syndrome type 18 (1 paper, 2025). "Homozygous variants in TCTN3 have been previously associated with Joubert syndrome type 18." (PMID 40565597, 2025).
Nystagmus (1 paper, 2022). Rhythmic, involuntary oscillations of one or both eyes related to abnormality in fixation, conjugate gaze, or vestibular mechanisms. "The genetic variants of TCTN3, CC2D2A, TMEM231, and TCTN2 were related to the clinical subgroups with nystagmus or retinopathy." (PMID 35456484, 2022).
polydactyly (1 paper, 2020). A disease characterized by the presence of polydactyly, including syndromic and non-syndromic forms. "The present study demonstrates that in complex CHD associated with polydactyly, the mutations of LTBP2 and TCTN3 may be potential pathological cause since these mutations are associated with changes of cellular functions that may affect the development of the heart." (PMID 33098376, 2020).
scoliosis (1 paper, 2022). A congenital or acquired spinal deformity characterized by lateral curvature of the spine. "TCTN3 mutations, which are less common molecular causes of JS, give rise to scoliosis, polydactyly, oral findings, horseshoe kidneys, and VSD." (PMID 36468023, 2022).
tumor (1 paper, 2023). "TAM greatly up-regulated (FC: 5.2) the expression of TCTN3 in the ovaries of tumor-bearing and CPA-treated rats." (PMID 37312040, 2023).
TCTN3 also shares sentences with these, for which no sentence is quoted: microphthalmia (2 papers); basal cell carcinoma (1); congenital heart disease (1); diabetes (1); retinopathy (1); Robinow syndrome (1).